RAB6D (RAB6D, member RAS oncogene family)
Description:
The small GTPases Rab are key regulators of intracellular membrane trafficking, from the formation of transport vesicles to their fusion with membranes. Rabs cycle between an inactive GDP-bound form and an active GTP-bound form that is able to recruit to membranes different sets of downstream effectors directly responsible for vesicle formation, movement, tethering and fusion.
Synonyms: WTH3DI; RAB6CL
Tractability: PROTAC: ubiquitination databases record sites on it.
Gene: Protein-coding gene on chromosome 2 (131,360,492 to 131,364,168, reverse strand). Ensembl gene ENSG00000233087.
Subcellular location (Human Protein Atlas): Golgi apparatus; Basal body
Gene Ontology:
Molecular function: GTPase activity; G protein activity; GTP binding
Biological process: intra-Golgi vesicle-mediated transport; protein localization to Golgi membrane; retrograde transport, endosome to Golgi; retrograde vesicle-mediated transport, Golgi to endoplasmic reticulum
Cellular component: cytosol
Genetic constraint (gnomAD): Loss-of-function variants: 9 observed, 13.95 expected, observed/expected ratio (o/e) 0.65, 90% interval 0.39 to 1.12. The synonymous counts are far from expectation, so gnomAD's model fits this gene poorly and the ratio says little. Missense variants: 144 observed, 235.2 expected, observed/expected ratio (o/e) 0.61, 90% interval 0.53 to 0.7. Synonymous variants: 57 observed, 85.64 expected, observed/expected ratio (o/e) 0.67, 90% interval 0.54 to 0.83.
Homologues: Paralogues in human: RAB6C (99% identical), RAB6A (74% identical), RAB6B (67% identical), RAB41 (48% identical), RAB8B (33% identical), RAB8A (32% identical), RAB5A (30% identical), RAB26 (30% identical), RAB5B (30% identical), RAB5C (30% identical), RAB10 (29% identical), RAB13 (29% identical), and 56 more.
Diseases named in the same sentence as RAB6D in open-access papers:
RAB6D is named in the same sentence as 1 disease in open-access papers, as found by Europe PMC text mining. Sharing a sentence is not in itself a finding about the gene and the disease. The quoted sentences say what the papers report.
tumor (1 paper, 2022). "The tumor-associated significance of the other seven genes (HIST2H2AA4, UQCRHL, AC008269.1, RAB6D, APOL4, HIST1H2AI, ANKAR, SGMS1) remains unclear." (PMID 35480120, 2022).